ANXA8 (annexin A8)
Description:
This protein is an anticoagulant protein that acts as an indirect inhibitor of the thromboplastin-specific complex, which is involved in the blood coagulation cascade.
Synonyms: ANX8; CH17-360D5.2
Tractability: Small molecule: it has a binding pocket of medium quality. Antibody: its Gene Ontology location is reachable by antibodies, with high confidence. PROTAC: ubiquitination databases record sites on it.
Gene: Protein-coding gene on chromosome 10 (47,460,162 to 47,484,175, reverse strand). Ensembl gene ENSG00000265190.
Subcellular location (Human Protein Atlas): Vesicles
Gene Ontology:
Molecular function: actin filament binding; calcium ion binding; calcium-dependent phospholipid binding; phosphatidylinositol-3,4,5-trisphosphate binding; phosphatidylinositol-3,4-bisphosphate binding; phosphatidylinositol-4,5-bisphosphate binding; phospholipase A2 inhibitor activity; protein binding; phosphatidylserine binding
Biological process: endosomal transport; endosome organization
Cellular component: cytosol; extracellular matrix; late endosome membrane; plasma membrane; sarcolemma; vesicle membrane
Genetic constraint (gnomAD): Loss-of-function variants: 5 observed, 14.48 expected, observed/expected ratio (o/e) 0.35, 90% interval 0.18 to 0.73. The upper end of that interval is the gene's LOEUF score, 0.73, which puts it in group 2 of 6, group 1 being the genes least tolerant of losing a copy. Missense variants: 44 observed, 112.81 expected, observed/expected ratio (o/e) 0.39, 90% interval 0.31 to 0.5. Synonymous variants: 26 observed, 38.11 expected, observed/expected ratio (o/e) 0.68, 90% interval 0.5 to 0.95.
Homologues: Orthologues: rabbit ANXA8 (93% identical), rat Anxa8 (93% identical), mouse Anxa8 (92% identical), dog ANXA8L1 (88% identical), Drosophila melanogaster AnxB9 (48% identical), Drosophila melanogaster AnxB11 (43% identical), zebrafish anxa13 (41% identical), zebrafish anxa13l (39% identical), zebrafish anxa14 (27% identical). Paralogues in human: ANXA8L1 (99% identical), ANXA5 (54% identical), ANXA4 (54% identical), ANXA11 (52% identical), ANXA6 (51% identical), ANXA7 (49% identical), ANXA3 (49% identical), ANXA13 (46% identical), ANXA2 (45% identical), ANXA1 (43% identical), ANXA10 (38% identical), ANXA9 (35% identical).
Diseases named in the same sentence as ANXA8 in open-access papers:
ANXA8 is named in the same sentence as 58 diseases in open-access papers, as found by Europe PMC text mining. Sharing a sentence is not in itself a finding about the gene and the disease. The quoted sentences say what the papers report.
breast carcinoma (12 papers, 2009 to 2022). "Evidence has shown AnxA1, AnxA2, AnxA8 are associated with the basal-like phenotype and potentiates poor prognosis of basal-like breast cancer." (PMID 29416802, 2018). "To better understand ANXA8’s association with this breast cancer subgroup we established ANXA8’s cellular distribution in the mammary gland and ANXA8’s effect on cell proliferation." (PMID 25803307, 2015). "Its expression is therefore strongly associated with a luminal epithelial progenitor cell population that is thought to be the origin of basal-like breast cancers, a subgroup of breast cancers with which ANXA8 is strongly associated." (PMID 25803307, 2015). "ANXA8 is strongly expressed in BRCA1-associated breast cancers and these cancers have recently been shown to originate from ERα−ve luminal progenitor cells." (PMID 25803307, 2015). "Moreover we found that high ANXA8 expression is also associated with clinical features of breast cancer progression (e.g., positive nodes, tumor stage, and tumor grade)." (PMID 30678048, 2019). "Our data therefore identify ANXA8 as a potential mediator of quiescence in the normal mouse mammary ductal epithelium, while its expression in basal-like breast cancers may be linked to ANXA8’s association with their specific cells of origin." (PMID 25803307, 2015). "It has been reported that ANXA8 expression is apparently upregulated in breast cancer, with a great relevance of tumor stages, grades and positive lymph nodes 17-19." (PMID 32284751, 2020). "Throughout the years of investigation Annexin A1 (AnxA1), Annexin A2 (AnxA2), Annexin A3 (AnxA3), Annexin A4 (AnxA4), Annexin A5 (AnxA5), Annexin A6 (AnxA6), and Annexin A8 (AnxA8) have all been identified as potential modulators of breast cancer progression." (PMID 29416802, 2018). "ANXA8’s reduced expression in the majority of breast cancers is consistent with an anti-proliferative role of ANXA8." (PMID 25803307, 2015). "RT-PCR on RNA from FACS-sorted cells and double-IF showed that ANXA8+ve cells were a subpopulation of c-kit +ve luminal progenitor cells, which have recently been identified as the cells of origin of basal-like breast cancers." (PMID 25803307, 2015). "Annexin A8 has been shown to be consistently over-expressed in acute promyelocytic leukaemia, breast cancers, pancreatic cancer by a combination of gene expression microarrays and immunohistochemistry." (PMID 19691830, 2009). "Therefore, biomarkers such as RA-regulated miRNAs targeting ANXA8 would have several advantages over hypermethylated markers of RA-resistant breast cancer." (PMID 32823855, 2020). "Subsequently, ANXA8 was extensively studied in the context of the mammary gland and breast cancer." (PMID 32823855, 2020). "Elegant studies were conducted to monitor ANXA8 upregulation during mouse mammary gland development and involution, as well as in a large group of patients with breast cancer and in subpopulations with transiently quiescent c-kit positive luminal cells of the ductal mammary epithelium." (PMID 32823855, 2020). "Given our results and the association of ANXA8 expression with ER−ve breast cancers it will be worth testing whether ANXA8 over-expression in ER+ve breast cancer cell lines can induce cellular quiescence or reduce proliferation." (PMID 25803307, 2015). "ANXA8 has been reported to be up-regulated in BRCA1-related breast cancer and PDAC." (PMID 26318045, 2015). "As this cell population was recently identified as the likely cells of origin for basal-like breast cancers, ANXA8’s expression in this cancer subgroup may therefore be a consequence of their cells of origin and thus a useful diagnostic marker." (PMID 25803307, 2015). "Further work will establish whether ANXA8 is functionally involved in progenitor cell quiescence and/or maintenance, and whether ANXA8 positive mammary epithelial cells may be the origin of ANXA8-expressing basal-like breast cancers." (PMID 25803307, 2015).
breast carcinoma (continued). "In addition, ANXA8 expression significantly correlated with features of breast cancer progression such as tumor grade, stage and lymph node infiltration, arising as a putative biomarker to identify ER-negative basal-like breast cancers." (PMID 36247003, 2022). "ANXA8 expression was also found significantly higher in DCIS relative to atypical ductal hyperplasia (ADH), and normal breast tissue, and was also associated with clinical features of breast cancer progression (e.g., positive nodes, tumor stage, and tumor grade)." (PMID 30678048, 2019). "In fact, ANXA2 downregulation and ANXA8 upregulation were jointly sufficient to create abnormal ductal carcinoma in situ (DCIS) acinar-like structures, which resemble early breast cancer lesions." (PMID 36247003, 2022). "However, ANXA8 is significantly upregulated in breast DCIS relative to atypical ductal hyperplasia (ADH) and normal breast tissue, and it is also associated with clinical features of breast cancer progression (e.g., positive nodes, tumor stage, and tumor grade)." (PMID 30678048, 2019). "ANXA8 expression is significantly upregulated in ductal carcinoma in situ (DCIS), which is an early form of breast cancer, and this protein was identified as one of the putative biomarkers in breast cancer." (PMID 32824294, 2020). "As shown hereafter, both ANXA2 and ANXA8 are not confined to acute promyelocytic leukemia and breast cancer, but are also involved in other cancers." (PMID 32823855, 2020). "Remarkably, being ANXA8 significantly overexpressed in DCIS versus normal tissue, it could be a valuable biomarker to infer ongoing physiological RA cancer-promoting action in breast tissue samples before breast cancer onset." (PMID 27894085, 2016).
ovarian carcinoma (9 papers, 2012 to 2024). A malignant neoplasm originating from the surface ovarian epithelium. "High ANXA8 levels were significantly associated with advanced stages, differentiation grade and nodal metastases, and proposed as a poor prognosis biomarker in epithelial ovarian cancer." (PMID 36247003, 2022). "Taken together, results suggested that ANXA8 was most closely associated with ovarian cancer tumorigenesis and progression." (PMID 31474227, 2019). "COX regression model analysis suggested that high ANXA8 expression was an independent risk factor affecting the survival and prognosis in patients with epithelial ovarian cancer." (PMID 31474227, 2019). "The IHC results showed that ANXA8 expression was higher in the malignant tumor group than in the borderline and benign tumor groups and normal ovary group, and high ANXA8 expression was an independent risk factor for survival and prognosis of ovarian cancer patients (P = 0.013)." (PMID 31474227, 2019). "Therefore, ANXA8, which is associated with these immune molecules, may provide a new target for studying the immune evasion of ovarian cancer cells and can potentially serve as a immunotherapeutic target for ovarian cancer." (PMID 31474227, 2019). "In addition, our preliminary prediction based on microarray data suggested that ANXA8 may be closely associated with ovarian cancer tumorigenesis and progression." (PMID 31474227, 2019). "ANXA8 is highly expressed in patients with several malignancies, such as ovarian cancer and bladder cancer." (PMID 39290334, 2022). "Immunohistochemical ANXA8 expression in malignant ovarian tumors correlated with FIGO stages and tumor progression, and it was revealed as an independent predictor of outcome and survival and a powerful poor prognosis biomarker for these tumors." (PMID 36247003, 2022). "A recent study showed that members of the Annexin family, including ANXA8, are involved in ovarian cancer tumorigenesis and progression." (PMID 32823855, 2020). "It has also been clarified that high expression of ANXA8 in pancreatic cancer 20-22 and ovarian cancer 23 was correlated with tumor cell invasion and proliferation." (PMID 32284751, 2020). "Combining the results of three databases, ANXA2 and ANXA8 mRNA expression levels were upregulated in ovarian cancer and the expression levels increased significantly with advanced FIGO stages." (PMID 31474227, 2019). "ANXA8 is a high candidate as a biomarker for early diagnosis, immunotherapy, and prognostic judgments of ovarian cancer." (PMID 31474227, 2019). "Our study was aimed at exploring the clinical significance of ANXA8 and providing a theoretical basis for the early diagnosis, prognostic judgments, and targeted therapy of ovarian cancer." (PMID 31474227, 2019). "We also validated the expression of ANXA8 in ovarian cancer by performing IHC assays and analyzed relationships between its expression with clinicopathological parameters, survival, and prognosis in patients with ovarian cancer." (PMID 31474227, 2019). "The correlation between ANXA8 expression and ovarian cancer was further validated using various databases." (PMID 31474227, 2019). "IHC assays demonstrated that ANXA8 was found mainly in the cell membrane and cytoplasm, and was highly expressed in epithelial ovarian cancer." (PMID 31474227, 2019). "We validated the expression of ANXA8 in ovarian cancer via IHC assays and analyzed its correlation with clinicopathological parameters and prognosis." (PMID 31474227, 2019). "A Cox regression model was adopted to analyze relationships between the survival times of ovarian cancer patients with ANXA8 expression, age, clinical stage, lymph node metastasis, degree of differentiation, and the pathological type." (PMID 31474227, 2019). "ANXA8 was significantly highly expressed in ovarian cancer, and high ANXA8 expression was significantly correlated with poor prognosis." (PMID 31474227, 2019).
ovarian carcinoma (continued). "Eighty-one patients with epithelial ovarian cancer were divided into high ANXA8-expression groups (++/+++) and low ANXA8-expression groups (−/+)." (PMID 31474227, 2019). "We conducted a preliminary screen for differentially expressed genes in three ovarian cancer cell lines and found that ANXA8 was upregulated in cell lines with greater malignancy and drug resistance." (PMID 31474227, 2019). "In this study, we analyzed Annexins in ovarian cancer using different databases and selected Annexin A8 (ANXA8), which showed the greatest prognostic value, for subsequent validation in immunohistochemical (IHC) assays." (PMID 31474227, 2019). "Therefore, ANXA8 expression is significantly related to poor prognosis and has been considered a strong candidate as a novel biomarker and therapeutic target for ovarian cancer." (PMID 38275362, 2023). "In ovarian cancer, ANXA8 expression was also found to increase during tumor progression." (PMID 36247003, 2022). "Based on a large study, ANXA8 might qualify as a novel biomarker for the early diagnosis, immunotherapy, and prognostic assessment of ovarian cancer." (PMID 32823855, 2020). "Our data revealed that ANXA8 was significantly highly expressed in malignant ovarian tumor tissues and that high ANXA8 expression was significantly correlated with poor prognosis in patients with ovarian cancer." (PMID 31474227, 2019). "Therefore, ANXA8 has the greatest correlation with prognosis in patients with ovarian cancer and is extremely closely related to ovarian cancer tumorigenesis and progression." (PMID 31474227, 2019). "Therefore, ANXA8 is a high candidate as a novel biomarker and therapeutic target for ovarian cancer." (PMID 31474227, 2019). "Therefore, we infer that ANXA8 and its co-expressed genes jointly regulate ovarian cancer tumorigenesis and progression through a complex regulatory network." (PMID 31474227, 2019). "Multivariate analysis indicated that the high ANXA8 expression (P = 0.013), late FIGO stages (P = 0.037), and poor differentiation (P = 0.049) were independent risk factors affecting the survival and prognosis of patients with epithelial ovarian cancer." (PMID 31474227, 2019). "Similarly, elevated ANXA8 levels have been observed in ovarian cancer tissues, where it may play a role in cell migration, lymphocyte infiltration, and immune modulation." (PMID 39716068, 2024). "In addition, ANXA8 expression in ovarian cancer was evaluated and validated using clinical samples." (PMID 31474227, 2019). "Therefore, ANXA8 may prove to be a novel biomarker for the early diagnosis, immunotherapy, and prognostic judgment of patients with ovarian cancer." (PMID 31474227, 2019). "The Oncomine database showed that ANXA8 mRNA expression level was significantly upregulated in ovarian cancer, and the TISIDB database showed that ANXA8 mRNA expression increased significantly with advanced FIGO stages." (PMID 31474227, 2019). "Both databases showed that ANXA2, ANXA3, ANXA8, and ANXA11 mRNA expression levels were upregulated in ovarian cancer compared with normal tissues, while ANXA5,ANXA6, and ANXA7 mRNA expression levels were downregulated." (PMID 31474227, 2019). "Annexin 8 (ANXA8) is involved in cell migration, cell adhesion, and vasculature development, as well as in the regulation of PI3K-Akt and focal adhesion in women with ovarian cancer." (PMID 38275362, 2023). "However, no report has demonstrated a correlation between ANXA8 expression and ovarian cancer." (PMID 31474227, 2019).
pancreatic cancer (8 papers, 2009 to 2023). "In pancreatic cancer, ANXA8 overexpression was also associated with higher histological grades and a lower survival in I-II stage patients, thereby emerging as a poor prognosis biomarker for early stages of pancreatic cancer." (PMID 36247003, 2022). "In some reports, ANXA8 was frequently overexpressed in pancreatic cancer, but its role in other cancers, including OSCC, is unclear, including OSCC and other oral‐related cancer." (PMID 37555363, 2023). "It was recently confirmed that ANXA8 induced HIF-1α transcription via calcium signaling pathways in pancreatic cancer, and can be regulated by zinc-finger transcription factor ZIC2 to inhibit apoptosis." (PMID 31474227, 2019). "On the other hand, ANXA8 has been reported to be frequently highly overexpressed in pancreatic cancer, but little is known about its function and significance in other human cancers, including OSCC." (PMID 26700817, 2016). "Both Claudin 18 and ANXA8 have emerged as new markers of pancreatic cancer." (PMID 32823855, 2020). "At the best of our knowledge, the role of ANXA8 in calcium fluctuation-mediated HIF-1α transcriptional activation and cell viability has been studied only in pancreatic cancer." (PMID 31429720, 2019). "ANXA8 expression was shown to be low or absent in normal pancreatic tissue, but was upregulated in pancreatic cancer." (PMID 32823855, 2020).
lung cancer (6 papers, 2009 to 2025). A malignant neoplasm involving the lung. "ANXA8, a protein from the Annexin family that associates with cell membranes, regulates the proliferation and migration of lung cancer cells through its effect on the EGFR-AKT-mTOR signaling pathway." (PMID 40243586, 2025). "In the Lung Cancer dataset, we succeeded in identifying highly discriminative genes (e.g., CALB2, HAS1, and ANXA8) implicated in the pathogenesis of MPM, ADCA, or other tumors." (PMID 19874631, 2009). "Similarly, in lung cancer, the overexpression of ANXA8 activates the EGFR/AKT/mTOR signalling pathway to promote proliferation, while in thyroid cancer, increased ANXA1 promotes thyroid cancer proliferation by mediating IL-6/JAK2/STAT3." (PMID 36936694, 2023).
bladder cancer (5 papers, 2021 to 2024). "Over-expression of miR-140-3p, targeting ANXA8, inhibits bladder cancer cell proliferation, migration, invasion, and EMT." (PMID 38952985, 2024). "For instance, overexpression of ANXA8 has been shown to promote cancer cell migration, invasion, and EMT in bladder cancer." (PMID 39716068, 2024). "The expression of ANXA1, ANXA2, ANXA3, ANXA5, ANXA6, ANXA8, and ANXA13 was closely related to basal-subtype bladder cancer, while the expression of ANXA4, ANXA9, ANXA10, and ANXA11 was closely related to luminal-subtype BC." (PMID 34484309, 2021).
cholangiocarcinoma (5 papers, 2014 to 2024). A carcinoma that arises from the intrahepatic biliary tree (intrahepatic cholangiocarcinoma) or from the junction, or adjacent to the junction, of the right and left hepatic ducts (hilar cholangiocarcinoma). "Downregulation of ANXA8 in the EGF-FOXO4 signaling pathway is involved in cholangiocarcinoma cell migration and tumor metastasis (Hata, Tatemichi & Nakadate, 2014)." (PMID 38952985, 2024). "EGF-mediated FOXO4 phosphorylation in cholangiocarcinoma leads to the transcriptional inhibition of ANXA8, FAK downregulation, and alteration of F-actin kinetics." (PMID 31474227, 2019). "FOXO4 can also inhibit growth factor-mediated tumor metastasis in cholangiocarcinoma by enhancing ANXA8 expression, which inhibits the migratory and metastatic characteristics of cholangiocarcinoma cells." (PMID 24864265, 2014). "For FOXO4, ANXA8 is transcriptionally down-regulated by EGF-mediated FOXO4 phosphorylation, which is correlated with the morphologic changes of EMT in the cholangiocarcinoma cells." (PMID 27976702, 2016).